GML (glycosylphosphatidylinositol anchored molecule like)
Synonyms: LY6DL
Tractability: Antibody: UniProt places it where antibodies can reach, with high confidence; its Gene Ontology location is reachable by antibodies, with high confidence; UniProt predicts a signal peptide or a membrane-spanning region.
Gene: Protein-coding gene on chromosome 8 (142,834,247 to 142,916,506, forward strand). Ensembl gene ENSG00000104499.
Subcellular location: Cell membrane
Pathways (Reactome):
Cellular responses to stimuli: Attenuation phase; HSF1 activation; HSF1-dependent transactivation; Regulation of HSF1-mediated heat shock response
Gene Ontology:
Biological process: apoptotic process; negative regulation of cell population proliferation
Cellular component: extrinsic component of membrane; plasma membrane
Genetic constraint (gnomAD): Loss-of-function variants: 0 observed, 0.52 expected, observed/expected ratio (o/e) 0, 90% interval 0 to 1.83. That is too few expected variants to judge how well the gene tolerates losing a copy. Missense variants: 95 observed, 115.51 expected, observed/expected ratio (o/e) 0.82, 90% interval 0.7 to 0.98. Synonymous variants: 40 observed, 44.88 expected, observed/expected ratio (o/e) 0.89, 90% interval 0.69 to 1.16.
Homologues: Orthologues: chimpanzee GML (98% identical), macaque GML (87% identical), dog GML (68% identical), rabbit GML (55% identical), mouse Gml (48% identical), mouse Gml2 (47% identical). Paralogues in human: LY6K (28% identical).
Diseases named in the same sentence as GML in open-access papers:
GML is named in the same sentence as 11 diseases in open-access papers, as found by Europe PMC text mining. Sharing a sentence is not in itself a finding about the gene and the disease. The quoted sentences say what the papers report.
follicular lymphoma (1 paper, 2023). Follicular lymphoma is a form of non-Hodgkin lymphoma characterized by a proliferation of B cells whose nodular structure of follicular architecture is preserved. "However, the capacity of pCLE to distinguish between GML and other types of small B cell lymphomas, like follicular lymphomas or mantle cell lymphomas, although extremely rare in the stomach, remains to be shown." (PMID 37568627, 2023).
gastric adenocarcinoma (1 paper, 2023). "Finally, the association between GML and gastric adenocarcinoma has been better documented, leading to the understanding of the importance of appropriate endoscopic surveillance of these patients, implicating the crucial role of a Gastroenterologist–Endoscopist in their management." (PMID 37568627, 2023).
tumor (3 papers, 2014 to 2022). "Mit-GML significantly induced the targeted delivery of Mit to tumor cells with overexpression of LHRH receptors which resulted in inhibition of tumor cell growth." (PMID 34207682, 2021). "Of these up-regulated genes, the greatest impact was on the expression of CIDEA (14.0-fold increase, p<0.0067), GML (26.4-fold increase, p<0.0004), and IP6K3 (18.1-fold increase, p<0.0001) in the LS-174T tumor xenografts." (PMID 25268703, 2014).
GML also shares sentences with these, for which no sentence is quoted: AIDS (1 paper); atherosclerosis (1); cancer (1); Hypertension (1); infection (1); lymphoma (1); mantle cell lymphoma (1); resistant hypertension (1).